EGFR (epidermal growth factor receptor)
Diseases named in the same sentence as EGFR in open-access papers (continued):
Sharing a sentence is not in itself a finding about the gene and the disease.
vulvar carcinoma (11 papers, 2009 to 2024). "Other targeted therapies such as EGFR inhibitors may have a role in the treatment of vulvar cancer as high levels of EGFR amplification are linked to poor overall survival." (PMID 38093798, 2023). "For instance, only malvidin which features methoxy groups at the 3′ and 5′ positions of the B-ring lead to inhibition of cAMP-specific phosphodiesterases (PDEs) whereas, cyanidin and delphinidin were shown to inhibit EGFR in human vulva carcinoma A431 cells." (PMID 34926717, 2021). "The EGFR overexpression or gene amplification is frequently reported in vulvar carcinoma, and it is usually related to a worse prognosis." (PMID 34439215, 2021). "The use of anti-EGFR agents, such as erlotinib, was tested in advanced vulvar cancer in a phase II study, with disappointing results, reporting only 27% of objective responses." (PMID 34439215, 2021). "This percentage is higher than previous studies; in particular, in one of the most important works on EGFR IHC expression in vulvar cancers, positive staining for EGFR was observed in 68% of the tumors." (PMID 34944993, 2021). "Moreover, researchers from this same group showed the effect of an EGFR tyrosine kinase inhibitor (AG1478) alone and in combination with cisplatin on two vulvar cancer cells lines, and the growth inhibition was depending on EGFR expression, by inhibition of the activity of EGFR, AKT, ERK." (PMID 34439215, 2021).
Anxiety (10 papers, 2012 to 2025). Intense feelings of nervousness, tension, or panic often arise in response to interpersonal stresses. "We also performed double IF labeling to determine the effect of p-EGFR on liver tissue marker staining and found that the p-EGFR protein level was considerably higher in the anxiety group." (PMID 37686162, 2023). "After conducting the IHC and IF staining of p-EGFR in the liver tissue, we found a significant difference in the positive staining areas between the anxiety group and the control group." (PMID 37686162, 2023). "The IHC assay showed that liver damage increased the activation of EGFR, and p-EGFR staining showed considerable brown deposits in the rat liver of the anxiety group." (PMID 37686162, 2023). "miR-144-3p targets a number of genes including Pten, Spred1, EGFR, Nrf2, AQP1, NGF, Brg1 and Notch, which are implicated in the stress response, anxiety and mood stabilizer treatment." (PMID 34674715, 2021). "Our findings showed that anxiety-like behavior in rats might be involved in EGFR-mediated inflammatory signaling pathways." (PMID 37686162, 2023). "In this study, we showed that the EGFR-related signaling pathways and the HPA axis might be involved in the development of liver injury caused by anxiety-like behavior in rats." (PMID 37686162, 2023). "In our study, 17 core common targets of ACG and anxiety were predicted, of which ESR1, SRC, AKT1, MAPK8, EGFR, and MMP9 belong to the prolactin and estrogen signaling pathways." (PMID 35624976, 2022). "Although AKT1 and EGFR were predicted to be involved in anti-anxiety processes in our study, the two targets have not been shown to be directly involved in the anti-anxiety process." (PMID 35624976, 2022).
Arthritis (10 papers, 2011 to 2024). Inflammation of a joint. "Arthritic joints contain increased amounts of epidermal growth factor receptor (EGFR) protein, and polymorphisms in EGFR are associated with arthritis risk." (PMID 24670222, 2014). "We analyzed the localization and activation of EGFR in the DRGs and spinal cord in arthritis models in which we had previously extensively characterized pain behavior." (PMID 39000275, 2024). "In the second set of experiments, we focused on spinal EGFR labeling using material from mice with glucose-6-phosphate isomerase (G6PI)-induced arthritis." (PMID 39000275, 2024). "In a study of G6PI-induced arthritis in mice, spinal EGFR was observed to be barely activated during the initial pain phase of arthritis, but significantly activated during the chronic phase of arthritis." (PMID 39000275, 2024). "In the spinal cord of mice, little neuronal EGFR activation was observed in the early painful stages of arthritis, but strong EGFR activation was found in the chronic painful stage of arthritis." (PMID 39000275, 2024). "This completely unbiased approach should provide further evidence for the involvement of EGFR activation in arthritis pain." (PMID 39000275, 2024). "In this study, we aimed to investigate the impact of EGFR overexpression on the response to the thioredoxin inhibitor and arthritis medication, auranofin and glutathione inhibitor L-buthionine-sulfoximine (L-BSO)." (PMID 39001381, 2024). "We studied EGFR labeling and activation in normal animals and in two models of arthritis to gain insight into the potential dynamics of EGFR labeling and activation in a painful disease." (PMID 39000275, 2024). "GE11-PLGA conjugate-based NPs are specifically uptaken by EGFR-overexpressed fibroblast; such as synoviocytes; which are the primarily cellular component involved in the development of destructive joint inflammation." (PMID 30082640, 2018). "Downregulation of EGFR in DRG neurons in acute arthritis may limit nociception, but pronounced delayed activation of EGFR in the spinal cord may be involved in chronic inflammatory pain." (PMID 39000275, 2024). "In the present experiments, we tested the hypothesis that IL-6 signaling activates EGFR signaling in peripheral and spinal nociception and examined whether EGFR localization and activation coincide with pain-related behaviors in arthritis." (PMID 39000275, 2024). "We tested the hypothesis that EGFR is activated during arthritis, which is characterized by persistent mechanical hyperalgesia." (PMID 39000275, 2024). "Indeed the pleiotropic effects mediated by ligation of the EGFR family (for example, angiogenesis, inflammation and synovial invasion) and the expression of multiple EGFR ligands in RA suggest that pan-EGFR blockade is likely to have a broad beneficial effect in arthritis." (PMID 21982514, 2011). "Immunohistochemistry showed EGFR localization in most DRG neurons from normal rats, but significant downregulation in the acute and most painful arthritis phase." (PMID 39000275, 2024). "Second, we obtained detailed insights into the dynamics of EGFR localization and activation in DRG neurons and in the spinal cord during the course of arthritis." (PMID 39000275, 2024). "The first irreversible BTK kinase inhibitor PCI-32765, which has demonstrated the proof-of-concept for the anti-arthritis efficacy by direct inhibition of BTK kinase, also bears potent activities against BLK, BMX, EGFR, Her2, ITK, JAK3, TEC and others." (PMID 28352114, 2017). "The high pEGFR localization in neurons but not in astrocytes and microglia at day 42 of arthritis does not suggest an EGFR activation pattern typical of injury and neurodegeneration." (PMID 39000275, 2024). "Our results provide evidence that thrombin acts through the PAR1/PAR3 receptors and activates PKCδ and c-Src, resulting in EGFR transactivation and activation of PI3K, Akt, and finally AP-1 on the MMP-13 promoter, thereby contributing to cartilage destruction during arthritis." (PMID 24385683, 2013).
Arthritis (continued). "Thus, maintenance of severe acute arthritis pain was not critically dependent on sustained high levels of EGFR in DRG neurons." (PMID 39000275, 2024). "The present data invite investigation of whether inhibition of spinal EGFR activation may be a target for the treatment of chronic pain states in arthritis, which are sometimes difficult to treat with non-steroidal analgesics and cytokine neutralization." (PMID 39000275, 2024). "Notably, at day 42 of arthritis, highly activated EGFR was observed in neurons and not in microglial and astroglial cells." (PMID 39000275, 2024). "However, during the acute and most painful phase of arthritis, EGFR was downregulated in DRG neurons, suggesting that EGFR activation in peripheral sensory neurons is not a critical neuronal mechanism for the maintenance of severe pain." (PMID 39000275, 2024).
bone cancer (10 papers, 2014 to 2025). A primary or metastatic malignant neoplasm affecting the bone or articular cartilage. "To assess whether EGFR signaling is required for c‐Fos‐dependent bone tumors, we genetically attenuated EGFR signaling by breeding H2‐c‐fosLTR mice to mice carrying the hypomorphic Egfr waved‐2 allele (Egfrwa2/wa2), leading to reduced EGFR activation." (PMID 30361264, 2018). "We found that orthotopic bone tumors induced with the EGFR and c‐Fos expressing 143b OS cell line were responsive to anti‐EGFR treatment, whereas LM7 cells, which only express EGFR but not c‐Fos, did not respond to erlotinib." (PMID 30361264, 2018). "Tartrate‐resistant acid phosphatase (TRAP) staining further revealed that EGFR is dispensable for osteoclastogenesis in H2‐c‐fosLTR‐derived bone tumors (Fig EV2B)." (PMID 30361264, 2018). "H2‐c‐fosLTR/Egfrwa2/wa2 mice developed significantly less and smaller bone tumors, indicating that EGFR is essential for bone tumor initiation." (PMID 30361264, 2018). "Osteoblast‐specific EGFR deletion also led to reduced pRSK2, decreased pCREB and less c‐Fos‐positive cells in OS, as shown by IHC and Western blot analysis of bone tumors from 6‐ to 7‐month‐old mice (Fig EV2F)." (PMID 30361264, 2018). "Finally, the third cluster was formed by bone cancer cells that are characterized with the inversed correlation between EGFR dependency and the expression of metabolism genes." (PMID 36361596, 2022). "We found that EGFR signaling is essential in osteoblasts for bone tumor formation and progression." (PMID 30361264, 2018). "Next, we wanted to investigate whether constitutive activation of the EGFR pathway can enhance bone tumor formation." (PMID 30361264, 2018). "We identified 73 overlapping genes between ATBC exposure and bone cancer, subsequently prioritizing STAT3, EGFR, MMP9, MAPK1, and MMP2 as core targets." (PMID 40625361, 2025). "This study underscores the potential carcinogenic effects of ATBC in bone cancer, identifying key targets such as STAT3, EGFR, MMP9, MAPK1, and MMP2." (PMID 40625361, 2025). "Mechanistically, we found that EGFR is essential for proliferation, survival, and MAPK‐dependent activation of pCREB/c‐Fos in bone tumors of H2‐c‐fosLTR mice and in orthotopically injected human 143b OS cells, which are positive for both EGFR and Fos." (PMID 30361264, 2018). "Notably, among these core targets, STAT3, EGFR, MMP9, MAPK1, and MMP2 were identified as the top five targets based on MCC values, serving as the hub targets of ATBC-induced bone cancer." (PMID 40625361, 2025). "Since CXCR4 transactivates EGFR and HER2, we tested whether growth factor receptor signaling contributes to bone tumor growth." (PMID 27809841, 2016). "Because of the relatively low incidence rate of OS, clinical trials with inhibitors or antibodies against EGFR could not establish a clear therapeutic benefit in bone tumor formation, due to low statistical power." (PMID 30361264, 2018).
chronic pancreatitis (10 papers, 2008 to 2025). A chronic inflammatory process causing damage and fibrosis of the pancreatic parenchyma. "Conditioned media collected from the CA19-9 expressing organoids stimulated EGFR phosphorylation, suggesting a role for CA19-9 in EGFR mediated chronic pancreatitis." (PMID 34638463, 2021). "The positive ratios of EGFR expression in chronic pancreatitis, pancreatic preneoplasia and PDAC were significantly higher than those in adjacent non-tumor tissues (P = 0.019, P < 0.001, and P < 0.001, respectively)." (PMID 27556697, 2016). "Metaplastic lesions of chronic pancreatitis patients regularly express high levels of the epidermal growth factor receptor (EGFR) family and their natural ligands EGF and TGFα." (PMID 26697077, 2016). "Examination of chronic pancreatitis patient samples revealed an upregulation of epidermal growth factor receptor expression in metaplastic pancreatic lesions." (PMID 26697077, 2016). "This is consistent with a pro-survival role of ERK and JNK in ductal epithelia of a murine hereditary pancreatitis model, and of enhanced EGFR expression in chronic pancreatitis." (PMID 18254976, 2008). "TGF-A signalling through the epidermal growth factor receptor (EGFR) has been shown to activate pancreatic stellate cells and may contribute to chronic pancreatitis and pancreatic carcinogenesis." (PMID 40826447, 2025). "In a pancreatic tissue microarray (TMA) of 179 samples, EGFR was positively expressed in 20.8% (10/48) of normal pancreatic tissues and in 71.4% (5/7), 66.7% (14/21) and 78.6% (81/103) of the chronic pancreatitis, pancreatic preneoplasia and PDAC samples, respectively." (PMID 27556697, 2016). "High-level expression of EGFR and its ligands EGF and TGFα were observed in human chronic pancreatitis specimens, as well as the activation of the EGFR signaling pathway in the areas of ADM in mice." (PMID 37373094, 2023).
endometrial tumors (10 papers, 2003 to 2023). "EGFR plays a crucial role in cellular functions implicated in cancer development, and has been shown to be expressed in a large percentage of endometrial tumors." (PMID 20579378, 2010). "Finally, MUC1 and EGFR co-expression was associated with increased cellular proliferation in human endometrial tumors." (PMID 27092881, 2016). "In addition, expression of EGFR and HER-2/neu is associated with the aggressiveness of an uterine endometrial tumour, and expression of PCNA and Ki67 is correlated with clinical outcome." (PMID 12888828, 2003). "Here, we observed that SOX2 level correlates with EGFR expression in late-stage endometrial tumors and cancer cells, in which SOX2 expression promotes EGFR, forming a SOX2–EGFR feedback." (PMID 30510261, 2018). "In vivo delivery of antisense DNAs against LRIG2 promoted the Hec-1A endometrial tumor growth in a xenograft mouse model, and immunoblotting of these tumor extracts showed consistent modulation of AKT, EGFR, the BCL-2 family members, and p21." (PMID 29358688, 2018). "Overall, the percent of endometrial tumor tissue with observed MUC1 expression was 29.5% (± 3.7% SEM), EGFR expression was 40.2% (± 3.9% SEM) and MUC1/EGFR co-expression was 14.3% (± 2.2% SEM)." (PMID 27092881, 2016). "However, our results revealed that phospho-activation of the PI3K and EGFR pathways by LRIG2 contributes to inhibition of endometrial tumor growth, implying a non-canonical role for PI3K/AKT in opposing cell survival and proliferation." (PMID 29358688, 2018).
esophageal tumor (10 papers, 2012 to 2024). "Studies have shown that mutations and overexpression of EGFR are also present in esophageal neoplasms and are closely associated with disease progression." (PMID 39701957, 2024). "MEDI3622 was also previously investigated alone and in combination with anti-EGFR–targeting agents in preclinical colorectal and esophageal tumor models demonstrating promising antitumor activity." (PMID 36998455, 2023). "MEDI3622 was previously investigated alone and in combination with anti-EGFR–targeting agents in preclinical colorectal and esophageal tumor models demonstrating promising antitumor activity." (PMID 36860547, 2021). "Experimental therapeutics targeting facets of esophageal tumor biology beyond EGFR have also been demonstrated to impact autophagy." (PMID 31683722, 2019). "It was found that approximately 50-70% of esophageal tumors express EGFR protein when examined using immunohistochemistry (IHC), while 15-28% of specimens also exhibit EGFR gene amplification when examined using fluorescence in situ hybridization (FISH)." (PMID 27013591, 2016). "Of note, the groups were very small (4 patients had esophageal tumours with high expression of EGFR)." (PMID 26844548, 2016). "Taken together, our research suggests that Fv-LDP-D3 and Fv-LDP-D3-AE may be promising agents for the treatment of EGFR-positive esophageal tumors." (PMID 35416106, 2022). "In accordance with this speculation, Kim and colleges showed that EGFR-induced human esophageal tumor presents a strong TUNEL staining, what suggests that EGFR overexpression tends to induce apoptosis pathways in esophageal cells." (PMID 23207070, 2012).
Hand-foot syndrome (10 papers, 2019 to 2026). "As we previously reported, hand-foot syndrome was the strongest factor in decreasing QoL so that multi-kinase inhibitors, EGFR-TKI, and capecitabine require careful prevention, early detection, and daily medical care." (PMID 33161506, 2021). "In addition, trifluridine/tipiracil might be better tolerated compared to other oral fluoropyrimides such as capecitabine, which has a more pronounced side effect profile (e.g. hand-foot syndrome), especially in combination with an anti-EGFR antibody." (PMID 35897060, 2022). "Unlike hand-foot syndrome (HFS), which is localized to the hands and feet, EGFR inhibitor-induced skin disorders present with systemic symptoms." (PMID 40888993, 2025).
injury (10 papers, 2012 to 2025). Damage inflicted on the body as the direct or indirect result of an external force, with or without disruption of structural continuity. "Unraveling distal targets associated with different aspects of EGFR signaling will help to identify novel pharmacologic strategies that modulate cell death and simultaneously preserve beneficial EGFR-related mechanisms in acute lung injury." (PMID 36193076, 2022). "Based on the known pleiotropic effects of EGFR activation, including modulation of apoptosis in other models, this protective effect of EGFR inhibition in severe hyperoxia warrants further investigation of EGFR in additional forms of acute lung injury." (PMID 36193076, 2022). "Our data show clearly that the expansion of SVZ NPs following brain injury requires EGFR and IGF-1R co-signaling." (PMID 24904523, 2014). "Rats subjected to spinal cord trauma can be effectively treated with the potent EGFR blockers C225 and AG1478, through modulation of neuroinflammation and associated secondary damage." (PMID 22824323, 2012). "Conversely, EGFR activation has been shown to suppress epithelial cell apoptosis in an LPS model of acute lung injury, and EGFR inhibition with a tyrosine kinase inhibitor promoted airway epithelial cell apoptosis in a tumor necrosis factor- (TNF-) induced model of acute lung injury." (PMID 36193076, 2022). "The epidermal growth factor receptor (EGFR) plays an important role on hepatic protection in acute and chronic liver injury." (PMID 37227557, 2023). "The anti-apoptotic and protective roles of epidermal growth factor receptor (EGFR) in diseases, such as acute lung injury and liver injury, have been shown." (PMID 35732465, 2022). "Repurposing existing drugs or developing new therapeutics that activate or modulate the CD133, EGFR, and HIF1A may offer promising treatment strategies for hypoxia-induced kidney injury." (PMID 40141116, 2025).